KIT (KIT proto-oncogene, receptor tyrosine kinase)
Description:
Tyrosine-protein kinase that acts as a cell-surface receptor for the cytokine KITLG/SCF and plays an essential role in the regulation of cell survival and proliferation, hematopoiesis, stem cell maintenance, gametogenesis, mast cell development, migration and function, and in melanogenesis. In response to KITLG/SCF binding, KIT can activate several signaling pathways. Phosphorylates PIK3R1, PLCG1, SH2B2/APS and CBL. Activates the AKT1 signaling pathway by phosphorylation of PIK3R1, the regulatory subunit of phosphatidylinositol 3-kinase. Activated KIT also transmits signals via GRB2 and activation of RAS, RAF1 and the MAP kinases MAPK1/ERK2 and/or MAPK3/ERK1. Promotes activation of STAT family members STAT1, STAT3, STAT5A and STAT5B. Activation of PLCG1 leads to the production of the cellular signaling molecules diacylglycerol and inositol 1,4,5-trisphosphate. KIT signaling is modulated by protein phosphatases, and by rapid internalization and degradation of the receptor. Activated KIT promotes phosphorylation of the protein phosphatases PTPN6/SHP-1 and PTPRU, and of the transcription factors STAT1, STAT3, STAT5A and STAT5B. Promotes phosphorylation of PIK3R1, CBL, CRK (isoform Crk-II), LYN, MAPK1/ERK2 and/or MAPK3/ERK1, PLCG1, SRC and SHC1.
Synonyms: SCFR; PBT; CD117; C-Kit; MASTC
Tractability: Small molecule: an approved drug acts on it; a structure with a bound ligand is known; a high-quality ligand is known; it has a high-quality binding pocket; it belongs to a druggable protein family. Antibody: a drug acting on it is in phase 1 trials; its Gene Ontology location is reachable by antibodies, with high confidence; UniProt places it where antibodies can reach, with medium confidence; UniProt predicts a signal peptide or a membrane-spanning region; the Human Protein Atlas places it where antibodies can reach. PROTAC: it is named in the literature on targeted protein degradation; UniProt records ubiquitination sites on it; ubiquitination databases record sites on it; its protein half-life has been measured; a small molecule that binds it is known.
Target class: TK protein kinase group; Kinase; Tyrosine protein kinase PDGFR family; Protein Kinase; Enzyme
Chemical probes: AC710, IMATINIB, PD005094, PD081093, PD083097, PD083604, PD084004, PD084329
Safety:
Unwanted effects reported when the protein is acted on. In parentheses: how it was acted on, where the effect was seen, and who reports it.
Anaemia (inhibition; blood; source: Brennan et al. (2024))
Carcinogenicity (activation; source: Brennan et al. (2024))
cardiac disorder (inhibition; cardiovascular; source: Brennan et al. (2024))
haematotoxicity (inhibition; blood; source: Brennan et al. (2024))
mastocytosis (activation; source: Brennan et al. (2024))
neovascularization (activation; source: Brennan et al. (2024))
neutropenia (inhibition; blood/bone marrow; source: Brennan et al. (2024))
rash (inhibition; skin; source: Brennan et al. (2024))
thrombocytopenia (inhibition; blood/bone marrow; source: Brennan et al. (2024))
heart disease (cardiovascular system; source: Force et al. (2011))
Gene: Protein-coding gene on chromosome 4 (54,657,267 to 54,740,783, forward strand). Ensembl gene ENSG00000157404.
Subcellular location: Cell membrane (Isoform 1); Cell membrane (Isoform 2); Cytoplasm (Isoform 3)
Subcellular location (Human Protein Atlas): Plasma membrane; Nucleoli fibrillar center
Pathways (Reactome):
Disease: Constitutive Signaling by Aberrant PI3K in Cancer; Dasatinib-resistant KIT mutants; Imatinib-resistant KIT mutants; KIT mutants bind TKIs; Masitinib-resistant KIT mutants; Nilotinib-resistant KIT mutants; Regorafenib-resistant KIT mutants; Signaling by extracellular domain mutants of KIT; Signaling by juxtamembrane domain KIT mutants; Signaling by kinase domain mutants of KIT; Signaling by phosphorylated juxtamembrane, extracellular and kinase domain KIT mutants; Sorafenib-resistant KIT mutants; Sunitinib-resistant KIT mutants
Signal Transduction: PI5P, PP2A and IER3 Regulate PI3K/AKT Signaling; PIP3 activates AKT signaling; RAF/MAP kinase cascade; Regulation of KIT signaling; Signaling by SCF-KIT
Developmental Biology: Developmental Lineage of Mammary Gland Alveolar Cells; Developmental Lineage of Mammary Gland Luminal Epithelial Cells; Transcriptional and post-translational regulation of MITF-M expression and activity
Gene expression (Transcription): TFAP2 (AP-2) family regulates transcription of growth factors and their receptors
Gene Ontology:
Molecular function: cytokine binding; protein binding; protein homodimerization activity; transmembrane receptor protein tyrosine kinase activity; growth factor binding; protein tyrosine kinase activity; ATP binding; protease binding; protein kinase activity; SH2 domain binding; stem cell factor receptor activity
Biological process: actin cytoskeleton organization; cell chemotaxis; cytokine-mediated signaling pathway; Fc receptor signaling pathway; Kit signaling pathway; male gonad development; mast cell chemotaxis; mast cell degranulation; positive regulation of MAPK cascade; positive regulation of mast cell cytokine production; positive regulation of receptor signaling pathway via JAK-STAT; positive regulation of tyrosine phosphorylation of STAT protein; positive regulation of vascular associated smooth muscle cell differentiation; protein autophosphorylation; B cell differentiation; cell migration; detection of mechanical stimulus involved in sensory perception of sound; digestive tract development; embryonic hemopoiesis; erythrocyte differentiation; erythropoietin-mediated signaling pathway; hematopoietic progenitor cell differentiation; hemopoiesis; immature B cell differentiation; inflammatory response; and 38 more
Cellular component: cytoplasm; extracellular region; plasma membrane; receptor complex; acrosomal vesicle; cell surface; cell-cell junction; cytoplasmic side of plasma membrane; external side of plasma membrane
Genetic constraint (gnomAD): Loss-of-function variants: 15 observed, 96.1 expected, observed/expected ratio (o/e) 0.16, 90% interval 0.1 to 0.24. The upper end of that interval is the gene's LOEUF score, 0.24, which puts it in group 1 of 6, group 1 being the genes least tolerant of losing a copy. Missense variants: 768 observed, 1,155.8 expected, observed/expected ratio (o/e) 0.66, 90% interval 0.62 to 0.7. Synonymous variants: 408 observed, 429.17 expected, observed/expected ratio (o/e) 0.95, 90% interval 0.88 to 1.03.
Gene-disease validity (ClinGen):
ClinGen rates the evidence that KIT causes each of these diseases.
gastrointestinal stromal tumor (autosomal dominant): Definitive.
Cancer hallmarks: escaping programmed cell death (promotes); proliferative signalling (promotes); invasion and metastasis (promotes)
Homologues: Orthologues: chimpanzee KIT (99% identical), macaque KIT (98% identical), pig KIT (90% identical), dog KIT (89% identical), guinea pig KIT (86% identical), rat Kit (84% identical), mouse Kit (83% identical), rabbit KIT (75% identical), tropical clawed frog kit (56% identical), zebrafish kita (48% identical), zebrafish kitb (45% identical). Paralogues in human: CSF1R (39% identical), PDGFRA (35% identical), PDGFRB (33% identical), FLT1 (30% identical), KDR (30% identical), FLT3 (29% identical), FLT4 (29% identical), FGFR1 (23% identical), FGFR2 (23% identical), FGFR3 (23% identical), FGFR4 (21% identical), TEK (19% identical), and 41 more.
Diseases named in the same sentence as KIT in open-access papers:
KIT is named in the same sentence as 745 diseases in open-access papers, as found by Europe PMC text mining. Sharing a sentence is not in itself a finding about the gene and the disease. The quoted sentences say what the papers report.
gastrointestinal stromal tumor (839 papers, 2003 to 2026). "While most gastrointestinal stromal tumors are driven by oncogenic mutations in KIT or PDGFRA, 10-15% exhibit functional loss of the succinate dehydrogenase (SDH) complex and genome-wide DNA hypermethylation." (PMID 42191879, 2026). "Imatinib is the first-line treatment for advanced gastrointestinal stromal tumors (GISTs) harboring KIT or PDGFRA mutations." (PMID 41559406, 2026). "Gastrointestinal stromal tumors (GISTs) are mesenchymal tumors that develop in the gastrointestinal tract; KIT mutations are present in both canine and human GISTs." (PMID 40427321, 2025). "In other malignancies, such as EGFR T790M in non-small cell lung cancer or c-KIT secondary mutations in gastrointestinal stromal tumors, this has already translated into routine clinical practice." (PMID 40585845, 2025). "KIT mutations have also been linked to metastasis in various other cancers, including gastrointestinal stromal tumors (GIST), lung cancer, and acute myeloid leukemia." (PMID 39858514, 2025). "As the most common sarcomas, gastrointestinal stromal tumors (GISTs) are a diverse group of tumors that arise from mutually exclusive activating mutations in either KIT or PDGFRA." (PMID 40343114, 2025). "This case represents a rare instance of gastrointestinal stromal tumor (GIST) harboring a KIT Exon 13 mutation accompanied by secondary thrombocytosis." (PMID 40837560, 2025). "Oncogenic mutations of EGFR gene are frequent in non-small cell lung cancer, and KIT or PDGFRA activating alterations are a hallmark of gastrointestinal stromal tumors." (PMID 40514442, 2025). "A constitutively active mutant of the receptor protein tyrosine kinase KIT is a major cause of gastrointestinal stromal tumours (GISTs)." (PMID 40770227, 2025). "Gastrointestinal stromal tumors (GISTs) are mesenchymal tumors often driven by KIT or PDGFRA mutations." (PMID 40584566, 2025). "Although not through the blocking of Abl, imatinib is also approved for gastrointestinal stromal tumours (GISTs), characterized by activating mutations in receptor tyrosine kinase genes (most commonly in c-KIT) that increase the proliferation of tumour cells." (PMID 41155542, 2025). "Gastrointestinal stromal tumors (GISTs) are the most common mesenchymal tumors of the gastrointestinal tract, primarily driven by activating mutations in KIT (CD117) and platelet-derived growth factor receptor alpha (PDGFRA)." (PMID 40733131, 2025). "In gastric cancer, particularly in gastrointestinal stromal tumors (GISTs), mutations in the KIT gene are frequently observed." (PMID 40182050, 2025). "Primary activating mutations in KIT (exon 9/11) are key driver alterations in about 80% of gastrointestinal stromal tumors (GIST)." (PMID 40018846, 2025). "Gastrointestinal stromal tumors (GISTs) are prevalent malignant mesenchymal tumors of the gastrointestinal tract, with most cases associated with mutations in the KIT or PDGFRA genes." (PMID 40129918, 2025). "Beyond hematologic malignancies, Nilotinib has demonstrated efficacy in gastrointestinal stromal tumors harboring KIT exon 11 mutations." (PMID 40646517, 2025). "For example, although they are chemo-resistant, systemic therapy with KIT inhibitors such as imatinib is particularly effective in gastrointestinal stromal tumors (GISTs) which harbor KIT mutations." (PMID 40075735, 2025). "Tyrosine kinase inhibitors are the standard treatment for gastrointestinal stromal tumours (GISTs) with oncogenic mutations in the KIT protooncogene (KIT) and the Platelet-Derived Growth Factor Receptor Alpha (PDGFRA) genes." (PMID 39796641, 2024). "Mutations in the gene that codes for KIT protein are associated with the following diseases: high-grade glioma, piebaldism, gastrointestinal stromal tumor (GIST), mastocytosis, liver cell membrane autoantibody (LMA), melanoma, and germ cell tumors." (PMID 39767683, 2024).
gastrointestinal stromal tumor (continued). "While advanced gastrointestinal stromal tumors (GISTs) are primarily treated with tyrosine kinase inhibitors (TKIs), acquired resistance from specific mutations in KIT or PDGFRA frequently occurs." (PMID 39516322, 2024). "Most gastrointestinal stromal tumors (GISTs) are driven by activating mutations in KIT and PDGFRA or alterations in the succinate dehydrogenase (SDH) complex." (PMID 38730662, 2024). "Gastrointestinal stromal tumors (GISTs) are typically characterized by activating mutations of the KIT proto-oncogene receptor tyrosine kinase (KIT) or platelet-derived growth factor receptor alpha (PDGFRA)." (PMID 38191907, 2024). "Gain-of-function mutations of KIT are detectable in many cancers, including gastrointestinal stromal tumor (GIST), melanoma, seminoma, mastocytosis, and acute myeloid leukemia (AML)." (PMID 39456668, 2024). "Amplification and activating mutations in KIT are frequently observed in gastrointestinal stromal tumors (GISTs) and melanoma." (PMID 38962317, 2024). "Gastrointestinal stromal tumors (GISTs) arise from Cajal’s interstitial cell precursors and display a variety of genetic mutations, primarily in the KIT and PDGFRA genes." (PMID 39027749, 2024). "The development of sunitinib was brought by the development of resistance to imatinib in gastrointestinal stromal tumour potent caused by mutation of KIT." (PMID 38362147, 2024). "Gastrointestinal stromal tumor is known to be associated with alterations in the c-KIT and platelet-derived growth factor receptor genes and, if resectable, is treated in accordance with the modified Fletcher classification." (PMID 37861097, 2024). "On the other hand, avapritinib has shown durable clinical efficacy in the treatment of gastrointestinal stromal tumors (GIST) with activating mutations in KIT and PDGFRα, which were previously considered untreatable due to resistance to TKI35." (PMID 38532028, 2024). "Most gastrointestinal stromal tumors (GISTs) are found in older adults, and they are typically driven by activating mutations in KIT or PDGFRA receptor signaling." (PMID 39334573, 2024). "Beyond BCR::ABL1 mutations, genetic alterations have been critically evaluated for their role in conferring Imatinib resistance, especially in cancers like gastrointestinal stromal tumors (GISTs), where mutations in the KIT or PDGFRA genes are prevalent." (PMID 38607055, 2024). "Ripretinib (DCC-2618) is a novel type II tyrosine switch control inhibitor for the treatment of KIT-mutated cancers, including gastrointestinal stromal tumors (GISTs)." (PMID 38275618, 2024). "In gastrointestinal stromal tumors (GISTs), identifying prototypical mutations in the KIT/PDGFRA oncogenes, or in rare alternate genes, is essential for prognostication and predicting response to tyrosine kinase inhibitors." (PMID 39199677, 2024). "Gastrointestinal stromal tumors were recognized as a distinct tumor type in 1998, when Hirota et al6 identified gain-of-function mutations in KIT as a key oncogenic driver." (PMID 39158910, 2024). "Gastrointestinal stromal tumors (GIST) are rare mesenchymal tumors characterized by KIT or PDGFRA activating mutations." (PMID 37686582, 2023). "Gastrointestinal stromal tumors (GIST) are rare mesenchymal tumors characterized by KIT or PDGFRA mutations." (PMID 37686582, 2023). "Activating point mutations in c-KIT are well-documented in gastrointestinal stromal tumors and in colorectal cancer tissues, where the mutation positive rate was found 19% according to a recent report." (PMID 37064137, 2023). "KIT is a tyrosine kinase receptor‐encoding gene with its mutations occurring in about 75%–80% gastrointestinal stromal tumors (GIST), 9.5% in melanoma, and 3% in lung cancer." (PMID 36161776, 2023). "Masitinib is under clinical investigation in several human malignancies that harbor similar canine KIT mutations (i.e., gastro-intestinal stromal tumors, ovarian and prostate cancer)." (PMID 36839989, 2023).
gastrointestinal stromal tumor (continued). "Familial gastrointestinal stromal tumors (GISTs) are mesenchymal tumors of the digestive tract caused by germline gain-of-function mutations in the KIT gene or platelet-derived growth factor receptor alpha gene (PDGFRA)." (PMID 37870660, 2023). "Activating mutations in KIT (CD117) have been associated with several diseases, including gastrointestinal stromal tumors and mastocytosis." (PMID 36834926, 2023). "Approximately 8% of the gastrointestinal stromal tumors devoid of KIT/ PDGFRA mutations bear the BRAF mutation." (PMID 37454137, 2023). "Gastrointestinal stromal tumors (GISTs) frequently show KIT mutations, accompanied by overexpression and aberrant localization of mutant KIT (MT-KIT)." (PMID 37704840, 2023). "Cancers associated with KIT alterations include gastrointestinal stromal tumors (GISTs), melanomas, lung cancer, and seminoma testicular cancer." (PMID 36734129, 2023). "Subsequently, biallelic loss of DEPDC5 has been found to be common in gastrointestinal stromal tumors with reduced sensitivity to KIT inhibitors, indicating that such alterations can also act as secondary events related to drug resistance." (PMID 35822448, 2023). "KIT mutations have been reported in more than 90% of cases of mast cytosis, 80–85% of cases of gastrointestinal stromal tumor (GIST), 10–20% of cases of melanoma and 4–17% of cases of AML, primarily core-binding factor AML (CBF-AML; ~30%)." (PMID 36551764, 2022). "Gastrointestinal stromal tumours (GISTs) are the most common mesenchymal tumours of the gastrointestinal tract and are characterized by activating mutations of c-KIT or PDGFRa receptor tyrosine kinases (RTKs)." (PMID 36076237, 2022). "c-KIT mutations are associated with gastrointestinal stromal tumors (GIST), leukemia, lung cancer, and melanoma." (PMID 35954441, 2022). "Mutations in the c-KIT gene are found in mastocytosis and gastrointestinal stromal tumors (GISTs) in humans and in 20–30% of canine MCT6." (PMID 36138037, 2022). "The aberrant activation of KIT results in the deregulation of the signaling networks which has been associated with the progression of many cancer types such as melanoma, gastrointestinal stromal tumor, and stomach cancers." (PMID 36568162, 2022). "Conversely, the c-KIT mutation spectrum overlaps with those found in a gastrointestinal stromal tumor (GIST), and together with PDGFRA contribution (this case), a common mechanism of carcinogenesis is not excluded." (PMID 35621644, 2022). "Targeted therapy for c-KIT-mutated melanoma: The c-KIT gene mutation has been observed in gastrointestinal stromal tumours." (PMID 36232957, 2022). "In fact, the introduction of immunohistochemistry (IHC) helped to differentiate LMS from other gastrointestinal stromal tumors (GIST) by receptor tyrosine kinase (KIT)-mutation detection making gastric LMS a sporadic tumor recently." (PMID 36845229, 2022). "The majority of gastrointestinal stromal tumors (GISTs; 70–80%) have mutations in the KIT receptor tyrosine kinase gene resulting in constitutive ligand-independent activation of KIT intracellular signaling." (PMID 35050442, 2022). "Gastrointestinal stromal tumors (GISTs) are rare, mesenchymal tumors of the gastrointestinal tract, characterized by either KIT or PDGFRA mutation in about 85% of cases." (PMID 36142281, 2022). "Gastrointestinal stromal tumors (GISTs) are the most common mesenchymal tumors of the gastrointestinal tract, mostly driven by activating mutations in KIT or PDGFRα oncogenes." (PMID 35406604, 2022). "Activating mutations of KIT gene, commonly on the exon 8 and 17, are frequently found in gastrointestinal stromal tumor (GIST) and systemic mastocytosis, as well as CBF-AML." (PMID 35216478, 2022). "Mutations of KIT have been reported to be associated with hyperpigmentation and lentigines, mastocytosis, and gastrointestinal stromal tumors (GISTs)." (PMID 35692550, 2022).